IGF1 (insulin like growth factor 1)
Diseases named in the same sentence as IGF1 in open-access papers (continued):
Sharing a sentence is not in itself a finding about the gene and the disease.
melanoma (continued). "MiR-425 has been found to be capable of inhibiting melanoma metastasis through repressing the PI3 K-Akt pathway by targeting IGF-1 in melanoma." (PMID 30285885, 2018). "Our data clearly demonstrate that Nutlin-3 treatment completely inhibited the invasiveness of melanoma cells through an impaired IGF-1-mediated matrix metalloproteinases type 2 activation mechanism." (PMID 29946532, 2018). "As did TAB cells, recombinant IGF-1 significantly preserved the viability of melanoma cells against BRAFi and MEKi further supporting its role as a tumor-supportive TAB-cell phenotype-defining mediator." (PMID 28928360, 2017). "We demonstrated that IGF-1 limits the effects of MEK1/2 inhibition in melanoma cells, while siRNA, by preventing IGF-1R de novo synthesis with a proportional, balanced overall decrease of its signaling, greatly increases the efficacy of MAPK targeting." (PMID 29137261, 2017). "B-cell-derived IGF-1 is critical for resistance of melanomas to BRAF and MEK inhibitors due to emergence of heterogeneous subpopulations and activation of FGFR-3." (PMID 28928360, 2017). "Consistently, resistance of melanomas to BRAF and/or MEK inhibitors is associated with increased CD20 and IGF-1 transcript levels in tumors and IGF-1 expression in tumor-associated B cells." (PMID 28928360, 2017). "We observed an increased expression of IGF-1 in melanoma lesions from patients treated with either BRAFi alone or BRAFi/MEKi combination therapies and increased IGF-1 correlated well with higher expression of FGFR-3 and CD20." (PMID 28928360, 2017). "In melanoma cells, enhancing expression of miR-425 inhibited proliferation by targeting IGF-1, which plays important roles in the PI3K/AKT signaling pathway." (PMID 28984821, 2017). "Increase in CD20 and IGF-1 expressions was further confirmed in two cohorts of melanoma patients (GSE8401 and EGAS00001000992) who developed resistance to diverse therapies." (PMID 28928360, 2017). "We did not detect any endogenous insulin or IGF2 RNA or protein levels in any of the four melanoma cells tested, but our RT-qPCR studies revealed presence of IGF1 RNA that is supported by recent reports." (PMID 28223541, 2017). "To investigate the clinical significance of IGF-1 and TAB cells, we analyzed TCGA-SKCM melanoma data (n = 473) and observed a heterogeneous expression of B-cell signature genes and IGF1 between tumor samples." (PMID 28928360, 2017). "In agreement with recent comprehensive reports of IGF gene expressions in melanoma, we found low levels of IGF1 and very high levels (25-fold greater than GHR) of IGF1R and IGF2R expression (Figure 5a1)." (PMID 28223541, 2017). "Although GH-excess did not cause any consistent variation in the levels of the low amounts of IGF1 RNA detected, GHRKD resulted in a 2-fold [MDA-MB-435] to 8.6-fold [MALME-3M] increase of IGF1 RNA in the four melanoma cells (Figure 5b1)." (PMID 28223541, 2017). "PDGF, secreted by melanoma cells, furthermore stimulates the production and secretion of IGF-1, which stimulates the proliferation of melanoma cells." (PMID 27999823, 2016). "We previously showed that IGF-1 mediated tumor immune escape by decreasing the immunogenicity of the murine melanoma B16-F0 cell line." (PMID 27764776, 2016). "The contribution of IGF-1 to melanoma cell migration was shown to require the activation of PI3K by IGF-1R." (PMID 27102439, 2016). "We previously showed that IGF-1 facilitated immune escape by decreasing the immunogenicity of the murine melanoma B16-F0 cell line." (PMID 27764776, 2016). "In the study described here, we investigated the effects of IGF-1 downregulation on the stemness features of murine melanoma B16-F10 cells and their tumorigenic potential in an NSG mouse model." (PMID 27764776, 2016). "In summary, we report here that IGF-1 is a key player in melanoma tumorigenicity and response to anti-tumor therapies." (PMID 27764776, 2016).
melanoma (continued). "Epidemiological evidence suggests that high levels of circulating IGF-1 and IGF-1R expression are associated with a higher risk of several common cancers, including melanoma." (PMID 27764776, 2016). "The targeting of IGF-1 in melanoma appears promising for novel anti-cancer strategies, as IGF-1 favors EMT, which seems to be intimately linked to tumor cell stemness and resistance." (PMID 27764776, 2016). "Blocking the IGF-1 pathway would improve the immune response, decrease the metastatic potential of tumor cells and sensitize melanoma cells to conventional treatments." (PMID 27764776, 2016). "In this study, we establish a clear relationship between a pregnancy-associated protein PAPPA, melanoma and functional effects mediated through IGF1 that provides a plausible mechanism for accelerated melanoma progression during pregnancy." (PMID 25940796, 2015). "To assess the efficiency of NT219 as an inhibitor of IGF1 signaling and to explore its mechanism of action, we used the human melanoma cell line, A375." (PMID 24261972, 2014). "Recently, Hilmi and co-workers also demonstrated that IGF-1 promotes resistance to apoptosis in melanoma cells through an increased expression of BCL2, BCL-X (L), and survivin." (PMID 23915418, 2013). "In melanoma cells, IGF-1 has been shown to mediate resistance to anoikis, a form of programmed cell death, which is induced by anchorage-dependent cells detaching from the surrounding extracellular matrix." (PMID 23915418, 2013). "Eight years ago the IGF1/IGF1R pair was shown to lead to melanoma migration, and in fact IGF1R was recently identified as a potential target in melanoma using a phosphoproteomic screen." (PMID 22747855, 2012). "Insulin-like growth factor 1 (IGF-1) was shown by others to significantly increase melanoma cell migration in-vitro through activation of the IGF1R." (PMID 22747855, 2012). "The high incidence of expression of TGF-β, IL-8, IL-6, VEGF, PDGF-AA, OPN, IGF-1 and IL-15 by human melanoma supports consideration of these factors in future planning of therapy." (PMID 24281094, 2010). "Targeting the IGF-1/AKT axis could thus represent a promising approach to enhance anti-tumor immune responses in melanoma." (PMID 41429766, 2025). "The serum IGF1 concentration is greater in patients with melanoma than in healthy individuals." (PMID 39042294, 2024). "Additionally, the insulin-like growth factor-1 (IGF-1R) can contribute to BRAF resistance to targeted therapies in melanoma." (PMID 37174072, 2023). "That low IGF1 increases epithelial features of melanoma cells is consistent with our data." (PMID 36229674, 2022). "IGF1 has been shown to enhance melanoma cell resistance to cisplatin, in line with the prior data." (PMID 36479381, 2022). "Other hormonal dysfunctions involving growth factors, growth hormone–IGF-1 axes, or estrogens/estrogen receptor status have been reported in melanoma without a clear connection to endocrine tumors underlying MEN1." (PMID 36428828, 2022). "A query of human tumor transcriptomic data for 471 melanoma patients from The Cancer Genome Atlas (TCGA) dataset revealed a positive correlation of IGF1 and ABCC9, ABCG1, ABCB1, and ABCC4 with GHR expression, and ABCC1 with both GHR and IGF1R expression, supporting our observations." (PMID 35865483, 2022). "In human melanoma biopsy specimens, adherens junctions were seen exclusively in areas with low IGF1 levels, but not in NECTIN1-deficient tumors." (PMID 36229674, 2022). "However, the expression of miR-425 was lower in human melanoma compared to normal cells, it repressed the PI3K-Akt pathway by targeting IGF-1 lead to inhibits melanoma metastasis." (PMID 34124998, 2021). "Loss of the β1,6-GlcNAc-transferase GCNT2 that synthesizes the I antigen branches of N-acetyllactosamine chains was observed in melanomas, and a knockdown of GCNT2 activated the IGFR1-mediated signaling pathways and Tyr phosphorylation upon IGF1 induction in melanoma cells." (PMID 34069424, 2021).
melanoma (continued). "Therefore, at the late stage of melanoma development, melanoma cells are unresponsive to the growth stimulation by IGF-1." (PMID 34067929, 2021). "We proceeded to evaluate the effect of the GH/IGF-1 axis in vivo in mouse syngeneic model for melanoma in C57BL/6J male and female mice transgenic for bovine GH (bGH mice) and in mice insensitive to GH action due to a dysfunctional GHR ‘knock-out’ (GHRKO mice)." (PMID 33291663, 2020). "IGF‐1 inhibition prevented malignant cell proliferation, migration and invasion, and lung colony formation in immunodeficient mice through an epithelial‐mesenchymal transition process in melanoma." (PMID 32851683, 2020). "This study is the first to compare the different effects of GH and IGF-1 in melanoma in vivo." (PMID 33291663, 2020). "By inoculating this cell line into bGH and GHRKO mice, we were able to test the hitherto unknown role of GH and/or IGF-1 in melanoma progression in vivo." (PMID 33291663, 2020). "Analyses of two representative N-glycosylated protein families, insulin-like growth factor-1 receptor (IGF1R) and integrins, revealed that GCNT2/I-branched glycan modifications inhibited IGF-1 and ECM-mediated melanoma cell proliferation, survival, and associated downstream signaling pathways." (PMID 30135430, 2018). "Moreover, starvation induced reduction in circulating IGF1 is known to preferentially protect normal cells but sensitize melanoma cells to chemotherapy." (PMID 28223541, 2017). "The effect of TAB cells on melanoma heterogeneity and therapy resistance could be reversed by IGF-1 neutralization or FGFR-3 knockdown." (PMID 28928360, 2017). "Together, these data support a FGF-2-induced conversion of B cells into a tumor-supportive phenotype which, with IGF-1 as critical key growth factor, reciprocally provides sustained pro-inflammatory and pro-tumorigenic signals to melanoma cells leading to activation of FGFR-3." (PMID 28928360, 2017). "We then asked whether tumor cells treated with the BRAFi PLX4720 can induce IGF-1 in B cells as did untreated melanoma cells." (PMID 28928360, 2017). "Importantly, IGF-1 also stimulates the expression of cancer stem cell markers on melanoma cells, including CD20, CD133, and CD271." (PMID 29156643, 2017). "The IGF1/IGF1-R nexus could be targeted for the development of more efficient anti-melanoma treatments." (PMID 27764776, 2016). "IGF-1 blockade could, therefore, effectively interfere with the maintenance of stemness and chemotherapy resistance in melanoma." (PMID 27764776, 2016). "We investigated whether the modulation of IGF-1 levels affected the behavior of melanospheres, which are enriched in melanoma cells with tumor-initiating properties." (PMID 27764776, 2016). "In addition, total IGF-1R expression levels were markedly reduced by IT pretreatment for 24 h in the IGF-1-stimulated melanoma cells." (PMID 27323414, 2016). "Finally, we show that IGF-1 favors MIC features in melanoma and governs the tumor response to conventional therapies." (PMID 27764776, 2016). "However, the role of IGF-1 in the stem cell phenotype of some melanoma cells remains to be determined." (PMID 27764776, 2016). "IGF-1 can also induce migration, through increased production of IL-8 by melanoma cells." (PMID 25763355, 2015). "Our finding that IGF1 elicits EMT in melanoma cells is consistent with these studies." (PMID 25940796, 2015). "In addition, IGF-1 and IGF1R have been implicated in other canine cancers including osteosarcoma, malignant melanoma and testis tumors, suggesting a major role of the IGF system in canine oncology." (PMID 26449867, 2015). "Wogonin (15, 30 and 60 μM) could inhibit IGF-1-stimulated migrarion (5%, 30%, 47%) and invasion (15%, 31%, 63%) of B16-F10 melanoma cells in a concentration-dependent manner." (PMID 25203554, 2014).
melanoma (continued). "Moreover, by inoculating syngeneic B16-F10 tumors in either bGH mice (high serum GH and IGF1) or GHRKO mice (high serum GH, low serum IGF1), we confirmed that GH directly increases ABCB and ABCG type and IGF1 preferentially increases ABCC type of ABC transporters in melanoma." (PMID 35865483, 2022). "Here the authors provide data that show melanoma cells downregulate GCNT2 with consequent loss of I-branched glycans; this leads to the formation of extended i-linear glycans and enhances melanoma growth via increases, in part, by IGF-1- and extracellular matrix-induced signaling." (PMID 30135430, 2018). "Consistent with the presence of CICs, or melanoma-initiating cells (MICs), in melanoma, and the role of IGF-1 in mediating EMT, chemoresistance, and stemness, we hypothesized that IGF-1 was involved in the acquisition of stem cells, promoting treatment resistance and melanoma cell propagation." (PMID 27764776, 2016). "Collectively, these findings indicate that IGF-1 promotes metastasis not only by favoring proliferation, tumor cell mobility and dissemination, but also by maintaining stemness features crucial for the immune escape, chemoresistance and tumorigenicity of melanoma cells." (PMID 27764776, 2016). "Thus, as expected, IGF-1 promotes G1/S cell cycle progression and proliferation in melanoma cells." (PMID 27764776, 2016). "Resistance to BRAF and MEK inhibitors in melanoma has been correlated with elevated levels of CD20 and IGF-1 transcripts in the TME, alongside increased IGF-1 expression by B cells." (PMID 41285707, 2025). "Human melanoma cells secrete FGF-2, which in turn activates B cells to produce the growth factor IGF-1." (PMID 41285707, 2025). "When treating RAW264.7 macrophages alone or in co-culture with B16-F10 melanoma cells, we found that IFN-γ significantly decreased the amount of secreted IGF-1." (PMID 41429766, 2025). "In low IGF1 conditions and in the presence of NECTIN1, melanoma cells form robust cell–cell contacts through adherens junctions, which prevent them from leaving the niche." (PMID 36229674, 2022). "In the presence of high levels of IGF1, melanoma cells proliferate within the cancer cell niche regardless of NECTIN1 status, as demonstrated by previous reports examining the role of IGF1 in early melanoma lesions." (PMID 36229674, 2022). "Another signalling pathway involved in melanoma is the PI3K pathway, which is activated by the binding of insulin-like growth factor 1 (IGF-1) to insulin-like growth factor receptor 1 (IGFR-1)." (PMID 34680938, 2021). "The silencing of IGF1 re-sensitized melanoma cells to BRAF/MEK inhibition, suggesting that IGF1 plays a major role in developing drug resistance in that case." (PMID 34830951, 2021). "The current study is the first to suggest that IGF-1 has a role in specifically elevating the Abcc group of ABC transporters, while GH specifically elevates Abcb and Abcg type ABC-transporters in melanoma in vivo." (PMID 33291663, 2020). "High levels of IGF-1 and FGFR-3 have been found in biopsies of melanoma patients treated with BRAF inhibitors in monotherapy or in combination with MEK inhibitors and IGF-1, and its receptor (IGF-1R) are associated with resistance to MAPK inhibitors." (PMID 33036192, 2020). "Both B16-F10 mouse melanoma and SK-MEL-30 human melanoma cells express Ghr and Igf-1r RNA, while SK-MEL-30 also expressed GH1 and IGF-1 transcripts." (PMID 33291663, 2020). "In our previous report, we have demonstrated that lncRNA MHENCR competitively binds miR-425 and miR-489, and therefore upregulates their targets IGF1 and SPIN1 in melanoma." (PMID 34094894, 2020). "Melanoma A375 cells were incubated with different concentrations of Polyphyllin I (0, 1.5, 3.0, and 6.0 mg/L) and PI3K/Akt/mTOR signaling pathway activator IGF-1(20 mg/L)." (PMID 32733943, 2020).
melanoma (continued). "Using realtime RT-qPCR, immunocytochemistry and western blotting, we evaluated RNA and protein expression levels of GH and GHR, as well as IGF-1 and IGF-1R in human and mouse melanoma cell lines." (PMID 33291663, 2020). "Two of the nevomelanocytic cell lines responded highly to IGF1 treatment by upregulating most of the stemness marker genes studied, which is significantly different than NBMEL and melanoma cells." (PMID 30675361, 2019). "Together, these data suggest that GCNT2/I-branch expression modulates IGF-1 and RGD binding activity on melanoma cells to potentially regulate IGF1R- and integrin-related signaling." (PMID 30135430, 2018). "In contrast to normal immortalized and fresh NB cells from healthy individuals or melanoma patients, TAB cells produced IGF-1, as did fresh TAB, and a variety of other pro-tumorigenic/pro-inflammatory factors/cytokines including IL-1, VEGF, and PDGF." (PMID 28928360, 2017). "The clinical relevance of these in vitro data is supported by IGF-1 and CD20 co-expression in melanoma biopsies." (PMID 28928360, 2017). "Human melanoma cells constitutively produce the growth factor FGF-2, which activates tumor-infiltrating B cells to produce the growth factor IGF-1." (PMID 28928360, 2017). "IGF1 & IGF2 and their cognate receptors are important regulators of multiple human cancers, including melanoma." (PMID 28223541, 2017). "Further, in line with our observation that TAB cells induce drug resistance via IGF-1 and activation of the FGFR-3 receptor in tumor cells, drug resistance of melanoma cells was dependent on the presence of FGFR-3." (PMID 28928360, 2017). "Consistently, neutralization of IGF-1 in TAB and tumor cells co-culture rescued the sensitivity of melanoma cells to BRAFi and MEKi." (PMID 28928360, 2017). "Both these cell lines, in contrast to melanoma cells (DFB), exhibit quite a high nIGF-1R level after serum starvation and it increases only moderately upon IGF-1 stimulation." (PMID 27275536, 2016). "If such a system exists, the regulation of IGF-1R by RUNX2 shown in the present study would suggest the existence of a positive feedback loop of RUNX2/IGF-1/IGF-1R in melanoma cells, promoting melanoma migration and invasion." (PMID 27102439, 2016). "Accordingly, the overexpression of miR-425 inhibits melanoma metastasis, stemness properties and chemoresistance, by repressing the PI3K-Akt pathway by targeting IGF-1." (PMID 27764776, 2016). "However, the role of IGF-1 in melanoma metastasis remains unclear." (PMID 27764776, 2016). "We also report enhanced induction of EMT when TGF-β1 and IGF1 were combined, suggesting cooperation between TGF-β and IGF signalling to drive EMT during melanoma growth and metastasis." (PMID 25940796, 2015). "Previous studies have shown that IGF1 can elicit EMT in cancers, so we assessed the ability of IGF1 to induce an EMT in two epithelial-like melanoma cell lines LM-MEL-34 and LM-MEL-62, respectively." (PMID 25940796, 2015). "In support of this possibility, a microarray conducted by us identified IGF1 and PTEN as possible targets of TBX3 in vertical growth phase melanoma cells." (PMID 25595898, 2015). "For this purpose, melanoma cell lines were exposed to various cytokines (EPO, EGF, TGF-ß1, Heregulin-α, IGF-1, HGF, SCF, NGF) and then were subjected to qPCR analysis and flow cytometry." (PMID 24489649, 2014). "It is up-regulated in a dose-dependent manner in melanoma cells treated with IGF-1, which indicates a possible role of IGFBP2 in the pathogenesis of melanoma." (PMID 24282616, 2013). "This idea is supported by the report that melanoma is sensitive to IGF-1 at the early stage, but insensitive to IGF-1 at the late stage of development." (PMID 22720981, 2012). "Other factors that increased Eag expression and activity are Insulin like growth factor-1 (IGF1) in Breast (MCF-7) cells through the akt pathway and Arachidonic acid (AA)in melanoma cells." (PMID 21190577, 2010).